MTOR (mechanistic target of rapamycin kinase)
Diseases named in the same sentence as MTOR in open-access papers (continued):
Sharing a sentence is not in itself a finding about the gene and the disease.
diabetes (continued). "In type 2 diabetes mellitus, hyperinsulinemia and elevated insulin-like growth factor 1 (IGF-1) levels drive activation of the PI3K/Akt/mTOR pathway, enhancing cell survival and proliferation." (PMID 41139205, 2025). "Consistent with clinical observations, tacrolimus administration reliably induces diabetes in rodent models by disrupting key β-cell signaling pathways, including CaN/NFAT and PI3K/AKT/mTOR, which collectively impair β-cell function (51, –, 54)." (PMID 40492760, 2025). "It is well documented that diabetes and hyperglycemic conditions can suppress autophagy through dysregulation of key signaling pathways, particularly the PI3K/AKT/mTOR and AMPK pathways." (PMID 40660790, 2025). "This is the first study to analyse the sequence of the MTOR, TBC1D4, CACNA1E, SLC19A2 and KCNH6 genes in Polish patients with suspected MODY-X diabetes using the NGS method." (PMID 38932873, 2024). "BMSCs were incubated on fibrin scaffolds and implanted into the wound model of diabetes rats, and angiogenesis was promoted at the wound through the AKT/mTOR pathway." (PMID 39193338, 2024). "This review provides an overview of shared molecular mechanisms between diabetes and cancer as well as discusses established and emerging therapeutic anti-cancer agents targeting the PI3K/Akt/mTOR pathway in cancer management." (PMID 39410536, 2024). "The intricate interplay between diabetes and cancer involves shared molecular pathways like insulin signaling, AMP-activated protein kinase (AMPK), and the mammalian target of rapamycin (mTOR)." (PMID 39333445, 2024). "Canagliflozin (CAN), a sodium-glucose cotransporter 2 inhibitor, binds to mTOR and then inhibits mTOR phosphorylation and the expression of hypoxia inducible factor-1α (HIF-1α), reducing myocardial cellular lipotoxicity and heart injuries in diabetes." (PMID 38596692, 2024). "However, the dysregulation of mTOR signaling has negative implications, as it may be associated with many diseases such as cancer, diabetes, cardiovascular disease, and neurological diseases." (PMID 39056712, 2024). "Utilizing PPI topology analysis, mTOR, Parkin, AKT, Beclin-1, P62, LC3A, Pink-1, and PI3K were established as key targets for diabetes treatment." (PMID 39211336, 2024). "The PI3K/Akt/mTOR pathway is instrumental in managing the release of inflammatory factors, oxidative stress, cell apoptosis, and autophagy, notably affecting autophagy in diabetes mellitus (DM) cells." (PMID 39211336, 2024). "Key databases such as PubMed, Google Scholar, and Web of Science were searched using terms related to “cancer”, “diabetes”, “hyperglycemia”, “antidiabetic drugs”, “cancer drug inhibitors”, and “PI3K/AKT/mTOR signaling”." (PMID 39410536, 2024). "An interesting historical study found that inhibiting miR-7a activated mTOR signalling, which enhanced the proliferation of pancreatic islet cells in mice; the authors suggested that targeting the mir-7–mTOR axis may therefore have potential therapeutic value for treating diabetes." (PMID 39125612, 2024). "It was demonstrated that liraglutide protected against diabetes-induced neuronal loss and synaptic ultrastructure degradation in the hippocampus of DM mice with cognitive impairment and might promote autophagy via the AMPK/mTOR pathway in primary cultured mice hippocampal neurons." (PMID 36909158, 2023). "The inhibition of the mammalian target of rapamycin (mTOR) pathway with rapamycin (RAPA, mTOR inhibitor) has shown promising results in controlling diabetes-induced detrimental effects during acute myocardial I/R injury." (PMID 37240345, 2023). "In a high-fat diet-induced obesity/diabetes mouse model, evodiamine can mediate metabolism via the AMPK/mTOR signaling pathway." (PMID 38054830, 2023).
diabetes (continued). "Consistent hyperglycemia in diabetes induces activation/inhibition of diverse pathways, including polyol, hexosamine, AGEs, PARP, MAPK, mTOR, NF-κB and tumor necrosis factor-α (TNF-α) pathway, which contribute to the pathogenesis and progression of DN." (PMID 37920252, 2023). "Both EKE and GEKE can improve diabetes and kidney disease by improving hyperglycemia, oxidative stress, and kidney physiological indicators and regulating the Keap1/Nrf2/HO-1 and AMPK/mTOR pathways." (PMID 36832842, 2023). "Therefore, a good understanding of the mTOR pathway’s connectivity, its downstream effectors are of great importance toward our ability for genetic and pharmacological interventions for the amelioration of metabolic diseases, such as diabetes, obesity, and NAFLD." (PMID 36690274, 2023). "Pathways commonly activated by diabetes-related conditions include NF-κB, NLRP3 inflammasome, fractalkine/CX3CR1, MAPKs, AGEs/RAGE and Akt/mTOR." (PMID 36869375, 2023). "Islets proteomics demonstrated that DFEs in the OI vs. STZ groups were significantly enriched in diabetes, insulin secretion, insulin resistance, and in the HIF1-α, mTOR, and MAPK signaling pathways." (PMID 36918798, 2023). "Urolithin A alleviates diabetes and pancreatic damage by activating the AKT/mTOR pathway to regulate insulin signaling and autophagy to reduce oxidation, inflammation and apoptosis in the pancreas of type 2 diabetic mice." (PMID 36235858, 2022). "These targets are enriched in multiple pathways related to type 2 diabetes mellitus, including adipocytokine, AMPK, TNF, HIF-1, PI3K-AKT, NOD and TOLL-like receptors, mTOR, glucagon, and insulin signaling pathways." (PMID 36160451, 2022). "Meanwhile, liraglutide exhibited neuroprotective effects against diabetes-induced hippocampal neuronal injuries and cognitive impairment via the AMPK/mTOR pathway." (PMID 35371595, 2022). "It has been shown that some of the factors involved in the PI3K/Akt signaling pathway, such as mammalian target of rapamycin (mTOR) and glycogen syntheses kinase-3 (GSK-3), contribute also to glucose metabolism and wound healing processes in diabetes mellitus." (PMID 36286052, 2022). "Prominent genes were RHOA, AKT1, RAC1, MDM2, CDKN1A, and VEGFA, which play important roles in TGF-beta and mTOR signaling (KEGG database), signaling by Wnt and by NOTCH (Reactome database), and in complications in diabetes mellitus (DisGeNET database)." (PMID 35742976, 2022). "pmTOR S2448 and pS6 expression was decreased at 3 month of diabetes and PHL treatment recovered mTOR activity in the neuroretina as demonstrated by Western Blot and immunofluorescence assay." (PMID 33637094, 2021). "In diabetes, insulin resistance will lead to high glucose which can suppress AMPK activity and activate mTOR in procession." (PMID 34707685, 2021). "mTOR inhibition improves contractility via the chronic administration of PDE inhibitor in animals and patients with diabetes and restores the impaired response to adrenergic stimulation in DCM mice." (PMID 32775437, 2020). "Blockade of the mTOR pathway reduced glomerular α-smooth muscle actin expression, mesangial matrix accumulation, and renal hypertrophy in STZ-induced diabetes." (PMID 32455017, 2020). "Interestingly, growing evidence suggests that increased mTOR signaling leads to alterations of cellular metabolic signaling, which in turn contributes to the development of insulin resistance and obesity-related diseases, including diabetes, cardiovascular disorders, and cancer." (PMID 32093387, 2020).
diabetes (continued). "Patients with diabetes were less likely to receive mTOR-directed therapy, while patients with comorbid CHF, liver metastases or bone metastases were more likely to receive mTOR-directed therapy." (PMID 31174493, 2019). "BCAA serum levels are increased in patients with diabetes and AD and supplement of BCAA in the diet promoted the development of AD by regulating the accumulation of phosphorylated Tau protein in an mTOR-dependent manner." (PMID 29802157, 2018). "Drugs inhibiting mTOR have been reported to improve insulin resistance and NASH in rats with diabetes." (PMID 30469530, 2018). "There is aberrant signaling of mTOR during conditions like cancer, cardiovascular disease (CVD), and diabetes." (PMID 28413737, 2017). "Our data suggest that in the setting of diabetes, reduced IGF-1, impaired mTOR pathway activation and reduced IL-15 in the epidermis function coordinately to promote altered DETC homeostasis and delayed skin wound closure." (PMID 28729536, 2017). "To further understand the process of homeostasis of DETCs, including the coordinated roles of IGF, mTOR and IL-15, we examined homeostasis in the STZ mouse model of diabetes." (PMID 28729536, 2017). "Suppression of IL-15 and suppressed phosphorylation of several components of the mTOR pathway, including S6K and AKT, occur upon treatment of mice with STZ, which further supports their coordinate role in diabetes." (PMID 28729536, 2017). "mTOR increased upon hypertrophy only in both groups (by 2.3-fold in CTRL and by 92% in DM) and MuRF-1 decreased due to diabetes (by 29% in the contralateral muscle and by 57% in the hypertrophied muscle)." (PMID 29123487, 2017). "Blockade of KCa3.1 reversed diabetes-induced inhibition of autophagy, which was dependent on the PI3K/Akt/mTOR signaling pathways." (PMID 27029904, 2016). "Our results demonstrate that blockade of KCa3.1 was able to reverse diabetes inhibited tubular autophagy, which was mediated through inhibition of the activation of PI3K/Akt/mTOR signaling pathways." (PMID 27029904, 2016). "For example, the diabetes drug Metformin, an activator of AMPK-directed inhibition of Akt/mTOR-mediated proliferation and Cyclin D1 synthesis, reduces the incidence and progression of some cancers." (PMID 27840833, 2016). "TXNIP inhibition suppressed diabetes-induced BNIP3 expression and activation of the mTOR signaling pathway." (PMID 27381856, 2016). "Phosphorylation of Akt, mTOR and p70S6K were downregulated by diabetes leading to a decline in muscle mass, however, Acu-LFES countered the diabetes-induced decline." (PMID 26230945, 2015). "We found that Acu-LFES improves muscle regeneration by reversing the diabetes-induced suppression of IGF-1, p-Akt (protein anabolic markers), and p-mTOR (protein synthesis markers)." (PMID 26230945, 2015). "mTOR (mammalian target of rapamycin) is an important mediator of the effect of AKT in the contexts of metabolism, diabetes, cellular differentiation (as seen in T-cell mediated immunity), and also aging." (PMID 22680924, 2012). "In animal models of diabetes as well as in human type 2 diabetes, a down-regulation of AKT/mTOR signaling indicates impaired insulin signaling." (PMID 22969728, 2012). "Drugs used to treat diabetes (e.g., Metformin) or inhibit signal transduction pathways (e.g., Raf, MEK, PI3K, mTOR inhibitors) can inhibit cellular proliferation and cellular aging." (PMID 21422497, 2011). "Identifying the precise mechanism could have broad implications for diseases treated with mTOR inhibitors (e.g., cancer, autoimmune disorders, and transplantation) and emerging GSK3-targeted therapies (e.g., Alzheimer’s, diabetes, and bipolar disorder)." (PMID 41026602, 2025). "Notably, higher ERBB2 expression was observed in unmarried patients (100%), pre-menopausal women (73–72%), and those with diabetes or hypertension, suggesting hormonal and metabolic modulation via PI3K/AKT/mTOR and MAPK/ERK pathways." (PMID 41403731, 2025).
diabetes (continued). "Also, mTOR, nuclear factor NF-kappa-B (NFKB1) and RB1-inducible coiled-coil 1 (RB1CC1) are autophagy-related genes that affect diabetes pathogenesis." (PMID 40533788, 2025). "Hypertension and diabetes are affected by the use of calcineurin inhibitors (CNI) and corticosteroids (STR), while dyslipidemia is affected by the use of CNI, STR, and mammalian target of rapamycin (mTOR) inhibitor." (PMID 40432895, 2025). "Although agents targeting the HIF-1 pathway, such as Bevacizumab and mTOR inhibitors, show promise, directly targeting HIF-1α may increase diabetes complications." (PMID 39996906, 2025). "Our results are consistent with previous reports that the outer retina is adversely affected by diabetes and, importantly, suggested that MSC therapy with mTOR inhibitor pretreatment may help mitigate this outer retinal degeneration." (PMID 40952054, 2025). "Furthermore, CypB’s PPIase activity affects lipid metabolism through key pathways including AKT/mTOR and IRE1α-XBP1, helping to prevent and treat obesity-related metabolic disorders such as diabetes and hyperlipidemia." (PMID 39125345, 2024). "Moreover, the addition of metformin at an anti-diabetes dose resulted in a significant increase in the levels of p-AKT and p-mTOR in local diabetes wounds, therefore promoting the angiogenic potential of BMSCs." (PMID 39193338, 2024). "In diabetes, it is believed that the phosphatidyl inositol 3-kinase (PI3K)/protein kinase B (PKB/Akt)/mammalian target of the rapamycin (mTOR) signaling is widely acknowledged as a fundamental pathway regulating cell proliferation, differentiation, and apoptosis." (PMID 39403253, 2024). "CMV: citomegalovírus; DLP: dislipidemia; DM: diabetes mellitus; DP: desvio-padrão; HAS: hipertensão arterial; IC: intervalo de confiança; mTOR: proteína alvo da rapamicina em mamíferos; PCR: reação em cadeia de polimerase qualitativa; PO: pós-operatório; TxC: transplante cardíaco." (PMID 39016410, 2024). "Nevertheless, Ramasubbu and Devi Rajeswari indicated that RAGE may inhibit the mammalian target of rapamycin (mTOR) and phosphatidyl inositol 3-kinase-AKT (PI3K/AKT) signaling pathways during diabetes." (PMID 39335163, 2024). "Our study further demonstrates the ability of Brazil nut and metformin polytherapy to improve diabetes-induced alteration of the cardiac tissue, as seen from the reduced cardiac concentrations of p38 MAPK and MTOR in the heart of the diabetic rats that were given these interventions." (PMID 39239455, 2024). "Assessment of the mTOR level revealed a significantly greater level in patients with diabetes who have microvascular complications than in those without microvascular complications and in the control group." (PMID 39261960, 2024). "Similarly, in rats with co-morbidities of diabetes and depression, the PI3K/Akt/mTOR pathway-mediated hippocampal degeneration and increase in autophagy have been assigned to cognitive impairment." (PMID 38137892, 2023). "One of the main hypotheses involves the overproduction of insulin, characteristic of patients with diabetes, and the corresponding stimulation of the phosphatidylinositol-3-kinase/Akt/mammalian target of rapamycin (PI3K/Akt/mTOR) pathway." (PMID 36677437, 2023). "Diabetes increases mTOR activity in the kidney, probably due to reduced AMP-activated protein kinase signaling or decreased interaction between glyceraldehyde 3-phosphate dehydrogenase and Rheb, each of which promotes mTOR activation by Rheb." (PMID 35054991, 2022). "Moreover, we found that the effect of food allergy on diabetes is related to the inhibition of GLP-1 secretion and the up-regulation of the PI3K/Akt/mTOR/NF-κB P65 signaling pathway in the jejunum." (PMID 36496564, 2022). "Additionally, Zhang and colleagues, explain that Elabela treatment would be able to reduce renal inflammation induced by diabetes through the APJ receptor and activation of the PI3k/Akt/mTOR pathway." (PMID 36661503, 2022).
diabetes (continued). "Studies have uncovered the roles of mTOR in the function of β-cells and the progression of diabetes, and they suggest that mTOR has both positive and negative effects on pancreatic β-cells in the development of diabetes." (PMID 35625542, 2022). "Notably, the changes in the p‐mTOR, P62, Beclin‐1, and LC3‐II/LC3‐I ratio were more obvious in surgery‐treated rats with diabetes than in surgery‐treated rats." (PMID 34784444, 2022). "Diabetes worsens SARS-CoV-2 infection through mechanisms including impairing the pulmonary structure and function, disturbing the immune function, enhancing the expression of ACE2, overactivating the mTOR signaling, and inducing the furin levels." (PMID 34690930, 2021). "In this study, we considered the working hypothesis that the mTOR signaling pathway plays a role in the pathological upregulation of retinal VEGF and ROS observed in the course of diabetes." (PMID 33479328, 2021). "The detected increase in mRNA mTOR protein kinase levels, as well as mTOR protein level in PLN cells under diabetes, may be a trigger for cell differentiation into effector pro-inflammatory subpopulations Th1 and Th17." (PMID 32341701, 2020). "Nevertheless, autophagy was significantly induced in adipose tissue of diabetes compared with non-diabetes, as well as decreased mTOR expressions in adipose tissue of diabetes cases." (PMID 32660483, 2020). "In addition, medical factors such as diabetes, high body mass index (BMI), delayed graft function (DGF), use of mammalian target of rapamycin (mTOR) inhibitors and acute rejection have been associated with lymphocele formation." (PMID 32887366, 2020). "Thus, among overexpressed pathways common to both tumor and mucosa, we found the mammalian target of rapamycin (mTOR), AMP‐activated kinase (AMPK), and tumor necrosis factor (TNF) signaling, already proposed to link diabetes, obesity, and cancer." (PMID 30628165, 2019). "There is a (small) chance that our findings are subject to confounding by indication; severe diabetes and not insulin is related with increased p-mTOR and IGF1R expression." (PMID 29486734, 2018). "To determine whether a similar pathway of mTOR and IL-15 suppression may explain the reduced DETC homeostasis in the STZ diabetes model, we examined the effects of diabetes induction over a timecourse of STZ treatment." (PMID 28729536, 2017). "In the epidermis, IL-15, IGF-1, and mTOR are known to regulate the maintenance of DETCs; however, it is unclear how these molecules may intersect to regulate DETC homeostasis in diabetes." (PMID 28729536, 2017). "This diabetes-induced IRS2 downregulation could, by means of inhibiting the Akt-mTOR axis, contribute to the observed reduction in HIF-1α total protein level." (PMID 25381014, 2015). "In this study, we provide evidence that hyperactivation of Akt/mTOR and significant decreased in tuberin resulted in significant decrease in DNA repair enzyme (OGG1) and accumulation of oxidative DNA damage in kidney cancer patients with diabetes." (PMID 24797175, 2014). "Additionally, we evaluated the downstream target of AKT, including the protein expression, mRNA expression, and phosphorylation levels of mTOR in HFpEF patients with and without diabetes." (PMID 40369521, 2025). "Metabolic diseases, such as obesity and diabetes, increase oxidative stress through mechanisms that include advanced glycation end-product (AGE) deposition, activation of protein kinase C (PKC), and dysregulation of the mammalian target of rapamycin (mTOR) signaling pathway." (PMID 40806733, 2025). "Furthermore, OA has positive effects on diabetes via increasing PI3K/Akt and AMPK phosphorylation, phosphoenolpyruvate carboxykinase (PEPCK), and G6Pase levels, as well as decreasing the level of the mammalian target of rapamycin (mTOR)." (PMID 38398510, 2024).